DMD (dystrophin)
Diseases named in the same sentence as DMD in open-access papers (continued):
Sharing a sentence is not in itself a finding about the gene and the disease.
myocarditis (8 papers, 2011 to 2025). Myocarditis is a condition that is characterized by inflammation of the heart muscle (myocardium). "This emergent safety concern was recently highlighted in several AAV-micro-dystrophin trials in which some patients with large dystrophin deletions developed immune-mediated myositis and myocarditis 24–42 days after dosing." (PMID 37033976, 2023). "Protease 2A released by the coxsackievirus can cleave dystrophin resulting in myocarditis, illustrating one of the common pathogeneses of myocarditis." (PMID 26066469, 2015). "In addition, for a subset of patients with deletions removing the N-terminal part of the protein, an immune response to the micro-dystrophin was observed that resulted in rhabdomyolysis and myocarditis." (PMID 36911945, 2023). "Using a murine model of myocarditis, we used both echocardiography and microCT to assess the extent of myocardial involvement in murine myocarditis using both wild-type mice and CVB cleavage-resistant dystrophin knock-in mice." (PMID 27486657, 2016). "Myocarditis is decreased in the heart when CVB3 is not able to cleave Dystrophin as demonstrated in the CVB3 infected DysKI mouse heart." (PMID 27486657, 2016).
myositis (8 papers, 2008 to 2025). "On the other hand, a study in transgenic mice with severe myositis reported the increased expression of miR-142-3p, which was associated with the upregulation of nuclear factor-kB (NF-κB)-regulated genes and the downregulation of dystrophin." (PMID 38929849, 2024). "Shared molecular pathologies of muscle inflammation and a secondary downregulation of dystrophin are seen in other muscle diseases such as myositis, LGMD, and myocardial infarction." (PMID 37534133, 2023). "We have demonstrated a similar mechanism in myositis where we observe reduced dystrophin and increased pathological miRNAs." (PMID 36628607, 2023). "Evaluation for neuromuscular disease (dystrophy, myositis), resulted in the discovery of mosaic immunostaining for dystrophin." (PMID 19530190, 2009). "Our findings may have implications for other muscle diseases that are characterized by reductions in dystrophin secondary to inflammation, such as myositis." (PMID 37534133, 2023). "Despite the still ongoing discussion regarding statin-induced myopathy, myositis, and rhabdomyolysis recent studies describe that the benefits of the treatment, outweigh the possible risks which, of note, are usually not relevant to DMD boys." (PMID 34479633, 2021).
myotonic dystrophy (8 papers, 2020 to 2025). An inherited progressive disorder affecting the muscles. "One study used ABE to edit the splice donor site of the myotonic dystrophy gene to skip the DMD exon 51 deletion mutation (∆Ex51), and PE was used to reconstitute the myotonic dystrophy protein ORF, thereby restoring myotonic dystrophy gene expression." (PMID 39081515, 2024). "Conjugates to improve delivery to skeletal muscle are also under preclinical investigation for single-stranded splice modulating AONs to induce DMD exon skipping or to reduce toxic RNA aggregates in myotonic dystrophy." (PMID 36269327, 2023). "NMD that were referred to as being part of the NBS programs were DMD, SMA, POMPE (Italy), Myotonic dystrophy (Spain)." (PMID 33568176, 2021). "Notably, AS of Dmd exon 78 is known to occur in patients with myotonic dystrophy (DM1), resulting in expression of the embryonic form of dystrophin and leading to defects in mobility and muscle architecture." (PMID 35165120, 2022).
progressive muscular dystrophy (8 papers, 2015 to 2025). "Deficiency of dystrophin, a protein involved in muscle membrane structure and flexibility, leads to progressive muscular dystrophy and degeneration in DMD patients and mdx mice." (PMID 25799359, 2015). "The dystrophin–utrophin knockout (dKO) model presents with a severe phenotype that closely recapitulates disease in patients, specifically severe progressive muscular dystrophy, premature death and a plenitude of physiological and molecular aberrations." (PMID 34389686, 2021). "DMD is a progressive muscular dystrophy due to the absence of dystrophin protein in muscle cells because of mutations in DMD gene (Xp21.2-p21.1) disrupting the reading frame or by generating a premature stop codon." (PMID 35608735, 2022). "Male pigs that carry a DMD gene lacking exon 52 replicate signs of human DMD pathology, including loss of dystrophin in skeletal muscle, progressive muscular dystrophy, increased serum creatine kinase levels and impaired mobility." (PMID 29419487, 2018).
Skeletal myopathy (8 papers, 2008 to 2024). "Five individuals with no skeletal myopathy had missense DMD variants of uncertain significance but potentially deleterious to dystrophin stability." (PMID 36154167, 2022).
brain tumors (7 papers, 2016 to 2024). "Some of the frequently mutated genes have been rarely reported in brain tumors according to the COSMIC database: EPH2B (67% vs 1.11%), DICER1 (67 vs 1.25%), KMT2B (67% vs 1.46%), ATRX (67% vs 13.95%) as well as several muscular genes (DMD, MYO10, MYO9B, MYH6) (P < .00001, Fischer exact test)." (PMID 39233831, 2024). "It was reported that IL1RAPL1 and DMD are two large genes located immediately adjacent to each other within the common fragile site region of instability, which are active in normal brain tissue but are under-expressed in every brain tumor cell line and xenograft." (PMID 35610583, 2022). "The two activated UPRs specific to GL261(scid) tumor responses have glial cell-related functions: DMD may relate to glial cell differentiation; and SPARC can inhibit brain tumor cell growth but also promotes invasion by increasing binding of extracellular matrix proteins." (PMID 27515027, 2016).
cardiac arrhythmias (7 papers, 2011 to 2024). Any disturbances of the normal rhythmic beating of the heart or MYOCARDIAL CONTRACTION. "Excessive lipofuscin accumulation in muscle has been reported in patients with chronic obstructive pulmonary disease and in dystrophin-deficient DMD patients and mdx mice." (PMID 24383498, 2014).
dystroglycanopathies (7 papers, 2015 to 2024). "Sarcoglycanopathies represent subtypes of limb–girdle muscular dystrophy that are caused by primary abnormalities in the dystrophin-associated sarcoglycans and alpha-dystroglycanopathies are associated with the abnormal glycosylation of alpha-dystroglycan." (PMID 33540575, 2021). "The Largemyd mouse model of dystroglycanopathy, in which there are defects in the glycosylation of α-dystroglycan (a component of the dystrophin-associated glycoprotein complex), has significantly more satellite cells than wild type control muscles, at 2–3 months of age." (PMID 25460248, 2015). "Severe dystrophic features were noted in cryosections of the muscle, and immunofluorescence studies showed an abnormal pattern of dystrophin-glycoprotein complex expression characteristic of a severe dystroglycanopathy." (PMID 27130732, 2016). "However, dystroglycanopathy mouse models lack DG-ECM linkage while retaining dystrophin and, therefore, are capable of anchoring microtubules to dystrophin." (PMID 38771868, 2024).
sarcoglycanopathies (7 papers, 2011 to 2024). "The pathogenicity interpretation of DMD missense variants becomes more complicated when they are detected in patients with overlapping clinical and pathological characteristics with sarcoglycanopathies." (PMID 38486238, 2024). "Six of our 9 enrolled patients (P4–P9), who were suspected of having a diagnosis of BMD or sarcoglycanopathy based on their clinical and pathological features, had only 6 predicted DMD missense variants." (PMID 38486238, 2024). "A secondary reduction in dystrophin expression has been described in sarcoglycanopathies, particularly in patients with pathogenic variants in β-, γ-, and δ-sarcoglycan." (PMID 39063034, 2024). "The main clue to differentiate patients with sarcoglycanopathy from BMD or manifesting carriers is a pattern of reduced labelling for SGs in the presence of normal dystrophin." (PMID 21798100, 2011). "However, reports of sarcoglycanopathy biopsies with abnormal labelling of dystrophin and β-dystroglycan exist." (PMID 21798100, 2011).
Turner syndrome (7 papers, 2012 to 2025). Turner syndrome is a chromosomal disorder associated with the complete or partial absence of an X chromosome. "The prevalence of DMD is less than 10 cases per 100,000 males and seems to be the same between regions, and DMD in females is very rare (<1 per million) and is limited to case reports of individuals with the Turner syndrome, a translocation involving DMD or those with bi-allelic DMD mutations." (PMID 36231658, 2022).
amyotrophic lateral sclerosis (6 papers, 2017 to 2025). Amyotrophic lateral sclerosis (ALS) is a neurodegenerative disease characterized by progressive muscular paralysis reflecting degeneration of motor neurons in the primary motor cortex, corticospinal tracts, brainstem and spinal cord. "Seeing as therapeutic modulation of the RhoA/ROCK pathway also improves disease phenotypes in neurodegenerative models such as amyotrophic lateral sclerosis and Parkinson's disease, the perturbed GC-KLF15-BCAA activity may not be limited to SMA and DMD." (PMID 29735415, 2018).
meningioma (6 papers, 2020 to 2023). A generally slow growing tumor attached to the dura mater. "Future functional work would be useful to identify specific roles of DMD variants in meningioma development." (PMID 33188621, 2021). "This suggests that DMD inactivation may be associated with high grade malignancy in meningioma." (PMID 33188621, 2021). "The findings in olfactory neuroblastoma are supported by a similar study evaluating DMD gene deletions in high grade/progressive meningioma patient samples." (PMID 33188621, 2021). "Of 12 samples harbouring DMD mutations, 11 had alterations in both copies of the neurofibromin 2 (NF2) gene, the most commonly mutated gene in meningioma, which encodes the tumour suppressor protein merlin." (PMID 33188621, 2021). "In addition, although our NGS panel enables a broad survey of known cancer genes, it does not screen for relevant genomic alterations such as DMD deletions or TERT gene translocations both of which have been shown to be associated with a poor outcome in progressive/high-grade meningiomas." (PMID 33087175, 2020). "DMD alterations were also found to be significantly more common in progressive/high grade meningiomas than in grade I and II non-progressive meningiomas." (PMID 33188621, 2021).
protein deficiency (6 papers, 2021 to 2025). "DMD is a fatal X-linked genetic disorder characterized by progressive muscular wasting resulting from dystrophin protein deficiency." (PMID 36619896, 2022). "LncRNAs regulate dystrophin expression and thus represent a potential therapeutic strategy to alleviate dystrophin protein deficiency." (PMID 36619896, 2022). "DMD is a result of mutations in the dystrophin gene that leads to dystrophin protein deficiency." (PMID 39158383, 2024). "Mutations in DMD gene can lead to a wide spectrum of clinical phenotypes, which are strongly correlated with the characteristics of molecular changes and the degree of dystrophin protein deficiency due to mutations." (PMID 35501714, 2022).
type II diabetes (6 papers, 2015 to 2024). "In fact, following training dystrophin levels in the lean subjects were similar to the levels found in obese and type 2 diabetics before training." (PMID 32358862, 2020).
depression (5 papers, 2023 to 2025). "DMD genes also intersect with depression and influence Alzheimer’s disease risk, suggesting a potential link to depressive symptoms, suicide rates, and cognitive deterioration in schizophrenia." (PMID 39202552, 2024). "The DMD gene has been demonstrated to be associated with depressive disorder, educational attainment, migraine and schizophrenia." (PMID 38035272, 2023).
fibrosis (5 papers, 2014 to 2026). the formation of excess fibrous connective tissue in an organ or tissue in a reparative or reactive process. "Masson's stain, HE staining, and dystrophin staining further revealed severe perivascular and myocardial fibrosis and cardiomyocyte hypertrophy in the LV myocardium of CHF." (PMID 34422210, 2021).
glioblastoma (5 papers, 2020 to 2026). The most malignant astrocytic tumor (WHO grade IV). "The 3′-rapid amplification of cDNA ends revealed 421 bp sequence in the downstream of DMD exon 41 in U-251 glioblastoma cells." (PMID 32443516, 2020). "Characterization of DMD transcripts in U-251 glioblastoma cells suggested the presence of a DMD transcript with its 3′ end in exons 41-45 (data not shown)." (PMID 32443516, 2020). "For instance, DMD expression is prognostic in low‐grade glioma (LGG) but not in the more aggressive glioblastoma." (PMID 40832923, 2026). "The effect of DMD gene expression on glioma survival was specific to only WHO grade II LGG; high-grade (grade III) anaplastic tumours and high-grade (grade IV) glioblastoma TCGA datasets did not result in any significant survival differences when stratified by high/low DMD expression." (PMID 35217778, 2022). "Several cancers of the nervous system were included in this study, revealing that DMD is significantly overexpressed in ependymoma and astrocytoma, but significantly under-expressed in medulloblastoma and non-significantly under-expressed in glioblastoma." (PMID 33188621, 2021).
leiomyosarcoma (5 papers, 2014 to 2024). An uncommon, aggressive malignant smooth muscle neoplasm, usually occurring in post-menopausal women. "WGS between uLMS and several benign variants have revealed some oncogenic alterations and research has revealed that the loss of the dystrophin gene is common in dedifferentiated leiomyosarcomas of gynecologic origin with poor outcomes." (PMID 39472980, 2024). "Their findings also revealed that dystrophin was detectable in a high proportion of leiomyomas, whereas its presence was significantly lower in leiomyosarcomas, detected in only 18% of cases." (PMID 39472980, 2024). "Furthermore, in order to validate our analyses with previous reported findings showing DMD deletions on myogenic tumors, we analyzed studies that performed gene expression microarrays on leiomyosarcomas and gastrointestinal stromal tumors (GIST)." (PMID 27391342, 2017).
leukemia (5 papers, 2017 to 2025). A malignant (clonal) hematologic disorder, involving hematopoietic stem cells and characterized by the presence of primitive or atypical myeloid or lymphoid cells in the bone marrow and the blood. "Interestingly, we also found that DMD was over-expressed in leukemias, renal carcinomas, ependymomas and astrocytomas." (PMID 27391342, 2017).
lymphoma (5 papers, 2021 to 2025). A malignant (clonal) proliferation of B- lymphocytes or T- lymphocytes which involves the lymph nodes, bone marrow and/or extranodal sites. "Lymphomas and lymphocytic leukaemia’s have both been linked to aberrant DMD gene expression." (PMID 33188621, 2021).
myasthenia gravis (5 papers, 2011 to 2025). Myasthenia gravis (MG) is a rare, clinically heterogeneous, autoimmune disorder of the neuromuscular junction characterized by fatigable weakness of voluntary muscles. "In several NMDs, including SMA, DMD and myasthenia gravis (MG), indirect costs have been estimated to account for 45%–80% of the overall disease burden." (PMID 41405177, 2025). "Increased expression of dystrophin was observed in experimental autoimmune myasthenia gravis." (PMID 21297967, 2011). "Compared to other NMD such as Myasthenia gravis (14,950€), CMT (17,427€), facioscapulohumeral muscular dystrophy (26,240€) and BMD (39,060€) total COI of ALS is notably higher, similar to those of DMD (78,913€) and SMA (70,566€)." (PMID 32532288, 2020).
myocardial infarction (5 papers, 2017 to 2025). Gross necrosis of the myocardium, as a result of interruption of the blood supply to the area, as in coronary thrombosis. "This hypothesis is supported by the significant association between the CTG repeat with MMP9, which is known to be a non-specific biomarker that has for instance been linked to cardiac remodeling after myocardial infarction, inflammation, and DMD." (PMID 36352383, 2022). "However, when faced with physiological stress resulting in greater than normal membrane damage, as in the case of DMD, or in stressors that are greater than normal, as in a myocardial infarction or other myocardial injury, pathological damage ensues." (PMID 38050701, 2024).
viral myocarditis (5 papers, 2014 to 2024). Myocarditis that is caused by an infection with a viral agent. "Moreover, in order to reveal the molecular network of ACTB regulating the hypertrophy of goose pectoral muscles, the viral myocarditis was identified as a pivotal pathway because it reflects the direct link between ACTB and DMD who can encode dystrophin protein." (PMID 39504833, 2024). "In addition, a DMD related pathway, the viral myocarditis pathway, was included." (PMID 25338682, 2014). "In viral myocarditis, STAT3 opposes the initiation of the dilated phenotype by maintaining membrane integrity via the expression of dystrophin." (PMID 30619368, 2018).
congenital muscular dystrophy (4 papers, 2014 to 2025). A muscular dystrophy that is characterized by diminished muscle tone (hypotonia), progressive muscle weakness and degeneration (atrophy), abnormally fixed joints, spinal rigidity, and delays in reaching motor milestones such as sitting or standing unassisted. "It is also involved in dystrophin localization and maintenance of sarcolemma integrity, and is proposed here as a candidate for congenital muscular dystrophy with merosin deficiency (MDC1B)." (PMID 25353622, 2014).
deafness (4 papers, 2013 to 2023). An inherited or acquired condition characterized by the complete loss of the ability to hear from one or both ears. "There were 18 genes linked only to Metabolic hearing loss (including four deafness genes: DMD, DUOX2, CELSR1 and ELMO3) and 54 genes linked only to Sensory hearing loss (including four deafness genes: ARHGAP21, LMO7, UBE3B and ADGRV1)." (PMID 38011198, 2023). "Mutations in families with DFNX3 deafness might occur in a novel gene located within the Xp21.2 locus, however, among families previously reported as having segregating HI that mapped to the DMD locus (Xp21.2), none presented with any of the typical clinical signs of DMD." (PMID 32543101, 2020).
hemophilia A (4 papers, 2014 to 2024). The most common form of hemophilia characterized by spontaneous or prolonged hemorrhages due to factor VIII deficiency. "Elevations in liver enzyme levels were reported as SAEs after clinical vector administration in clinical trials for DMD (n = 2), hemophilia A (n = 2), hemophilia B (n = 3), mucopolysaccharidosis (MPS) type IIIB (n = 1), and SMA (n = 4)." (PMID 39044426, 2024). "Although more than 15 different diseases were included in these clinical trials, the most common were hemophilia B (n = 8), SMA (n = 7), LCA (n = 5), DMD (n = 5), and hemophilia A (n = 3)." (PMID 39044426, 2024). "The susceptibility of many disease genes (such as DMD, ATM, NPC1 (Niemann-Pick disease), F9 (hemophilia A), F8 (hemophilia B)) to aberrant pre-mRNA splicing has spawned creative therapeutic approaches that have been the focus of a great deal of time and effort." (PMID 24456648, 2014). "Hemophilia A (F8 coding sequence − 7 kb), DMD (Dystrophin coding sequence − 14 kb) and skin disease Recessive Dystrophic Epidermolysis Bullosa (COL7A1 coding sequence − 9 kb) are examples of diseases for which replacement corrections of dysfunctional large genes could yield clinical benefits." (PMID 32883366, 2020).